CSPG4P12 (chondroitin sulfate proteoglycan 4 pseudogene 12)
Synonyms: CSPG4P9
Gene: Transcribed unprocessed pseudogene on chromosome 15 (85,191,438 to 85,202,009, forward strand). Ensembl gene ENSG00000259295.
Diseases named in the same sentence as CSPG4P12 in open-access papers:
CSPG4P12 is named in the same sentence as 7 diseases in open-access papers, as found by Europe PMC text mining. Sharing a sentence is not in itself a finding about the gene and the disease. The quoted sentences say what the papers report.
colorectal cancer (1 paper, 2024). A primary or metastatic malignant neoplasm that affects the colon or rectum. "Therefore, the aim of this study was to investigate the potential role of CSPG4P12 in colorectal cancer and explore the possible underlying mechanism." (PMID 38808892, 2024). "The overexpression of CSPG4P12 inhibited cell proliferation, invasion, and migration in colorectal cancer cells." (PMID 38808892, 2024). "The difference of CSPG4P12 expression between colorectal cancer tissues and adjacent normal tissues was analyzed using the online Gene Expression Profiling Interactive Analysis 2 (GEPIA2) database." (PMID 38808892, 2024). "Colorectal cancer tissues had lower CSPG4P12 expression than adjacent normal tissues." (PMID 38808892, 2024). "However, the function of pseudogene CSPG4P12 in colorectal cancer remains unclear." (PMID 38808892, 2024).
esophageal cancer (1 paper, 2024). A primary or metastatic malignant neoplasm involving the esophagus. "Recognizing this limitation, we will investigate the functional role of the CSPG4P12 rs8040855 variant in esophageal cancer in future research." (PMID 38877481, 2024). "In this study, we aim to investigate the correlation between the CSPG4P12 rs8040855 and the risk of esophageal cancer and to explore the effect of CSPG4P12 in the development of esophageal cancer." (PMID 38877481, 2024). "In this study, we also discovered the effect of genetic variants in CSPG4P12 gene on the susceptibility to esophageal cancer." (PMID 38877481, 2024). "We found that the low expression of CSPG4P12 was associated with the poor prognosis of esophageal cancer based on UCSC XENA data." (PMID 38877481, 2024). "The CSPG4P12 rs8040855 affected the risk of susceptibility to esophageal cancer." (PMID 38877481, 2024). "These will be crucial for elucidating the molecular mechanisms by which the CSPG4P12 rs8040855 variant contributes to esophageal cancer pathogenesis and could reveal novel targets for therapeutic intervention." (PMID 38877481, 2024). "In our investigation into the role of CSPG4P12 lncRNA in esophageal cancer, we assessed its expression across various esophageal cancer cell lines." (PMID 38877481, 2024). "Bioinformatic analysis revealed that the pseudogene CSPG4P12 is poorly expressed in many types of cancer tissue, including esophageal cancer." (PMID 38877481, 2024). "We then constructed CSPG4P12 overexpression vector to explore its role in the development of esophageal cancer." (PMID 38877481, 2024). "For future research, it would be advantageous to utilize esophageal cancer cell lines with naturally higher levels of CSPG4P12." (PMID 38877481, 2024). "In this study, our data showed that the pseudogene CSPG4P12 is lowly expressed in esophageal cancer tissues compared to adjacent normal tissues." (PMID 38877481, 2024). "Transwell assay indicated that CSPG4P12 significantly decreased the migration and invasion ability of esophageal cancer cells (P < 0.01)." (PMID 38877481, 2024). "To further explore the biological relevance of this finding, we investigated the expression levels of the CSPG4P12 gene in esophageal cancer tissues and adjacent normal tissues, revealing differential expression patterns that supported the potential functional impact of the rs8040855 polymorphism." (PMID 38877481, 2024). "This study also provided evidence that CSPG4P12 could inhibit the proliferation, migration, and invasion ability of esophageal cancer cells." (PMID 38877481, 2024).
esophageal squamous cell carcinoma (1 paper, 2024). Esophageal squamous cell carcinoma (ESCC) is a type of esophageal carcinoma (EC) that can affect any part of the esophagus, but is usually located in the upper or middle third. "This study aimed to evaluate the association of the CSPG4P12 polymorphism with esophageal squamous cell carcinoma (ESCA) risk and to explore the biological impact of CSPG4P12 expression on ESCA cell behavior." (PMID 38877481, 2024).
hepatocellular carcinoma (1 paper, 2024). A malignant tumor that arises from hepatocytes. "In a hepatocellular carcinoma (HCC) study, researchers demonstrated that CSPG4P12, combining 5 other genes (BX537318.1, TMEM147, AC015908.3, CEBPZOS, and SRD5A3), served as the signature for prognostic evaluation of HCC." (PMID 38877481, 2024).
cancer (2 papers, 2024). A tumor composed of atypical neoplastic, often pleomorphic cells that invade other tissues. "Chondroitin sulfate proteoglycan 4 pseudogene 12 (CSPG4P12) has been implicated in the pathogenesis of various cancers." (PMID 38877481, 2024). "To date, this is the first report on the association of CSPG4P12 polymorphism with the risk of any cancer." (PMID 38877481, 2024). "KEGG enrichment analysis of CSPG4P12 co-expressed genes showed that they were mainly enriched in cancer-related pathways such as G2M, MYC, and E2F." (PMID 38808892, 2024). "All these studies revealed a potential biological role of CSPG4P12 in the development of various cancers." (PMID 38877481, 2024). "The decreased expression of CSPG4P12 in CRC could be attributed to several molecular mechanisms that regulate gene expression in cancer." (PMID 38808892, 2024). "Concurrently, CSPG4P12 overexpression results in a significant reduction in the levels of Bcl-2, an anti-apoptotic protein that typically contributes to cell survival and resistance to cell death mechanisms in cancer cells." (PMID 38877481, 2024). "The downregulation of CSPG4P12 in CRC could, therefore, be a consequence of the cancer cells' attempt to escape the normal regulatory mechanisms that limit cell proliferation and promote differentiation." (PMID 38808892, 2024). "By decreasing CSPG4P12 expression, CRC cells may enhance the activity of the E2F and MYC pathways, promoting uncontrolled cell division and progression of the cancer." (PMID 38808892, 2024).
tumor (2 papers, 2024). "CSPG4P12, as a highly homologous pseudogene of CSPG4, most likely possesses a similar biological role to CSPG4 which has been demonstrated to play an important role in tumor cell growth and metastasis." (PMID 38877481, 2024).
CSPG4P12 also shares sentences with these, for which no sentence is quoted: lung carcinoma (1 paper).